LAMC2 (laminin subunit gamma 2)
Diseases named in the same sentence as LAMC2 in open-access papers (continued):
Sharing a sentence is not in itself a finding about the gene and the disease.
glioma (5 papers, 2017 to 2022). A benign or malignant brain and spinal cord tumor that arises from glial cells (astrocytes, oligodendrocytes, ependymal cells). "HDAC3 expression is associated with the presence of VM in glioma tissues and contributes to VM in gliomas, possibly through the PI3K/ERK and MMPs/LAMC2 pathways." (PMID 36294763, 2022). "Data obtained from our study indicated that conditioned medium from M2 cells (M2-CM) increased the tubule formation number in glioma cells, as well as VM marker expression, including LAMC2, MMP-9 and MMP-14." (PMID 27903982, 2017). "LAMC2 plays a key role in VM formation of glioma through the AKT and ERK (extracellular regulated protein kinases) signaling pathways, and it increases the malignancy degree of glioma." (PMID 36463205, 2022).
non-small cell lung carcinoma (5 papers, 2014 to 2026). A group of at least three distinct histological types of lung cancer, including non-small cell squamous cell carcinoma, adenocarcinoma, and large cell carcinoma. "In non-small cell lung cancer cells, the inhibition of Akt upregulates LAMC2 expression, while high LAMC2 suppresses Akt signaling." (PMID 34606473, 2021).
oral cancer (5 papers, 2020 to 2024). "In conclusion, our results showed that BBOX1-AS1 facilitates oral cancer cell proliferation and migration and suppresses apoptosis by upregulating LAMC2 expression by targeting miR-3940-3p." (PMID 35506252, 2022). "The miR5580-3p inhibits oral cancer cell immortality by suppressing LAMC2." (PMID 39578854, 2024). "However, whether LAMC2 is involved in ceRNA and regulates oral cancer progression remain unclear." (PMID 35506252, 2022). "By intersecting the predicted mRNAs of miR-3940-3p using the starBase algorithm and the differentially expressed mRNAs in oral cancer by analyzing GSE19089 with adjusted P < 0.05 and logFC ≥ 1.5, LAMC2 was identified." (PMID 35506252, 2022).
colon carcinoma (4 papers, 2017 to 2022). "These genes encode the extracellular matrix proteins LAMA3 and LAMC2, which have been detected in invasive colon cancer cells and are regulated by transforming growth factor beta 1 and the hepatocyte growth factor produced in the tumor microenvironment." (PMID 36077674, 2022). "It has been reported that the transcription factor of the AP-1 complex binds and regulates LAMB1 gene expression upon binding to its promoter in F9 mouse embryonal cells and LAMC2 in HT29 human colon cancer cells." (PMID 33435161, 2021). "LAMC2 encoded the laminin γ subunit, and research has shown that TGF-β1 might act on the promoter region of LAMC2 in colon cancer cells to promote its expression." (PMID 36463205, 2022).
epidermolysis bullosa (4 papers, 2018 to 2023). Epidermolysis bullosa (EB) is a group of genetic skin diseases that cause the skin to blister very easily. "Mutations of LAMA3, LAMB3, LAMC2, DST, and COL17A1 have been reported in heritable skin fragility disorders and epidermolysis bullosa (EB)." (PMID 36430582, 2022).
esophageal cancer (4 papers, 2016 to 2025). A primary or metastatic malignant neoplasm involving the esophagus. "In esophageal cancer, hypoxia-induced enhancement of histone H3K9la specifically increases the transcriptional activity of laminin subunit gamma 2 (LAMC2), thereby promoting tumor proliferation and invasion." (PMID 40589733, 2025). "Furthermore, DUXAP8 is positively related to MAGEA4, GABRA3 expression, and negatively related to INPP5A, TIMP4 expression in esophageal cancer; LINC00460 is positively related to ITGA3, LAMC2 expression, and negatively related to FOXO4, KLF15 expression in esophageal cancer." (PMID 29926523, 2018).
squamous cell carcinoma (4 papers, 2017 to 2025). A carcinoma arising from squamous epithelial cells. "For example, LAMC2, was involved in ‘cell differentiation’ and ‘metabolic process’ spatially patterned pathways in the human squamous cell carcinoma." (PMID 36243975, 2023). "TCGA and GEO database analyses showed that LAMC2 is highly expressed in both adenocarcinoma and squamous cell carcinoma patients, and its expression is negatively correlated with rate of survival." (PMID 37542131, 2023). "To validate these findings, we analyzed data from TCGA on other squamous cell carcinomas (CESC, ESCC, HNSC) and observed that expression levels of LAMC2 and Laminin‐332 genes were consistently higher in tumors than in normal tissues." (PMID 40470730, 2025).
acne (3 papers, 2018 to 2022). An inflammatory process of the sebaceous glands which is characterized by comedones, nodules, papules and/or pustules on the skin. "In contrast, at this locus the acne risk haplotype is associated with increased expression of LAMC2 in the skin, providing insight into the phenotypic consequence of the opposite extreme of an allelic series in this gene." (PMID 30542056, 2018). "An eQTL for LAMC2 in skin colocalises with the acne association signal at 1q25.3 (Pcoloc = 0.97)." (PMID 30542056, 2018).
head and neck cancer (3 papers, 2018 to 2023). A primary or metastatic malignant neoplasm affecting the head and neck. "LAMC2 is over-expressed in several types of cancers, including urothelial, lung, colorectal and head-neck cancers, and is associated with a poor prognosis." (PMID 30642292, 2019). "By targeting Lamin γ2 (LAMC2), miR-29a-3p was reported to suppress migration and invasion in head and neck cancers, and overexpression of LAMC2 was found to enhance invasiveness in vivo." (PMID 29599914, 2018). "LAMC2 was associated with CD8+ T-cell and B-cell infiltration in head and neck cancer." (PMID 37779898, 2023).
intrahepatic cholangiocarcinoma (3 papers, 2021 to 2025). A carcinoma that arises from the intrahepatic bile duct epithelium in any site of the intrahepatic biliary tree. "In certain cancers, notably intrahepatic cholangiocarcinoma, LAMC2 facilitates tumor growth and metastasis through molecular pathways including epidermal growth factor receptor (EGFR) signaling." (PMID 40725121, 2025). "In intrahepatic cholangiocarcinoma (iCCA), LAMC2 gene is amplified, leading to the increased levels of LAMC2 protein." (PMID 38526177, 2024).
keloid (3 papers, 2020 to 2024). An irregularly shaped, elevated mark on the skin caused by deposits of excessive amounts of collagen during wound healing. "Similar to the present findings in wounds, LAMC2 was the only LAM332 subunit with increased expression in vascular endothelial cells isolated from human keloid skin, where LAMC2 expression was positively correlated with vascularization." (PMID 37981221, 2024). "SERPINA3 and LAMC2 were the most upregulated genes in keloid VECs, and they contribute to fibrosis and inflammation in keloids." (PMID 37587491, 2023). "Our data suggest that SERPINA3 and LAMC2 upregulation in KVECs may contribute to the development of fibrosis and prolonged inflammation in keloid." (PMID 32850798, 2020). "In the present study, we identified the genes that are up- or down-regulated in KVECs and then focused on SERPINA3 and LAMC2, both of which are sharply up-regulated in KVECs and thus may contribute to keloid pathogenesis." (PMID 32850798, 2020). "For example, inhibiting LAMC2 early after onset may prevent the vascular permeability and prolongation of inflammation that drives keloid growth." (PMID 32850798, 2020). "Since LAMC2 promotes the proliferation and survival of cancer cells, and keloids are characterized by excessive fibroblast proliferation and resistance to apoptosis, we also asked whether LAMC2 secretion by VECs could promote keloid fibroblast proliferation and downregulate apoptosis." (PMID 32850798, 2020). "Immunohistochemical analysis of the six samples showed that all of the keloids had greater protein expression of both SERPINA3 and LAMC2 in the blood vessels than the normal skin samples." (PMID 32850798, 2020).
laryngeal carcinoma (3 papers, 2022 to 2024). Carcinoma that arises from the laryngeal epithelium. "Previously, LAMC2 has been reported to serve as a potential therapeutic target of cetuximab in laryngeal cancer." (PMID 37542131, 2023).
liver cancer (3 papers, 2020 to 2024). An epithelial or non-epithelial malignant neoplasm that arises from the liver. "Here we report that LAMC2, an extracellular matrix protein upregulated in many types of cancers, is localized in the ER of lung, breast, and liver cancer cells." (PMID 37891404, 2024). "Our study reports that LAMC2 is mainly localized in the endoplasmic reticulum of lung, breast, and liver cancer cells." (PMID 37891404, 2024). "Single‐cell RNA‐sequencing data of human liver cancers, including HCC and iCCA, portrayed a noticeably higher expression of LAMC2 in iCCA tumor cells compared to other pathological types of liver cancer cells and tumor immune microenvironment cells." (PMID 38526177, 2024). "Furthermore, from hydrodynamic tail vein injection (HDTV) orthotopic liver cancer mouse models driven by various oncogenes, RNA sequencing data showed that LAMC2 exhibited a significantly higher level in tumors from the iCCA‐like tumor subtype than HCC subtype and normal livers." (PMID 38526177, 2024). "Furthermore, by examining these signaling networks, we discovered that FOS (Fos proto-oncogene, AP-1 transcription factor subunit), LAMC2 (laminin subunit gamma 2), and CALML3 (calmodulin like 3) were the most significant gene nodes with high degrees involved in liver cancer." (PMID 32280695, 2020).
pancreatic adenocarcinoma (3 papers, 2021 to 2024). "Other researchers found that a combined signature of high LAMA3, LAMB3, and LAMC2 expression was a stronger predictor of poor prognosis in pancreatic adenocarcinoma than individual genes." (PMID 39218967, 2024). "We used Gene Expression Omnibus (GEO) database and identified six genes (COL1A2, ITGA2, ITGB6, LAMA3, LAMB3, and LAMC2) that could affect the survival rate of pancreatic adenocarcinoma patients." (PMID 35899199, 2022). "The mRNA expression levels of RUNX2, LAMC2 and FBXO32 showed significant differences between cancer and adjacent non-cancerous tissues especially in pancreatic adenocarcinoma (PAAD)." (PMID 34606473, 2021).
small cell lung carcinoma (3 papers, 2017 to 2023). Small cell lung cancer (SCLC) is a highly aggressive malignant neoplasm, accounting for 10-15% of lung cancer cases, characterized byrapid growth, and early metastasis. "KEGG pathway enrichment analysis also showed that LAMC2 is significantly associated with small cell lung cancer and ERBB signaling pathway." (PMID 37542131, 2023). "Laminin subunit gamma-2 appeared in the “ECM-Receptor Interaction”, “Small Cell Lung Cancer”, and “Focal Adhesion” pathways." (PMID 28697756, 2017). "In addition, there were 6 common KEGG pathways in the CIN-CC group (p < 0.01), namely, the adipocytokine signaling pathway, small cell lung cancer (ITGA6, PIAS3, and LAMC2), pathways in cancer, the Toll-like receptor signaling pathway, graft versus host disease, and the TGF-beta signaling pathway." (PMID 34174849, 2021).
anaplastic thyroid carcinoma (2 papers, 2023 to 2024). "For example, in anaplastic thyroid carcinoma, LAMC2 has been reported to bind EGFR to promote EGFR inactivation." (PMID 37542131, 2023). "Previously, LAMC2 and EGFR were only found to co-localize on the cell membrane in anaplastic thyroid carcinoma cells." (PMID 37542131, 2023).
chronic pancreatitis (2 papers, 2018 to 2022). A chronic inflammatory process causing damage and fibrosis of the pancreatic parenchyma. "The circulating levels of LAMC2 were significantly higher in patients with cystadenoma and chronic pancreatitis than in healthy donors, and PTX3—but not LAMC2—was detected in patients with IPMN." (PMID 35681634, 2022).
Hypodontia (2 papers, 2018 to 2022). The absence of five or less teeth from the normal series by a failure to develop. "FOXC2 is also predicted to positively regulate LAMC2 and MSX1, a highly conserved transcription factor well-known to regulate tooth formation, and causing tooth agenesis in humans when mutated." (PMID 35217915, 2022).
tongue cancer (2 papers, 2019 to 2025). A malignant neoplasm affecting the tongue. "Interestingly, however, the late-stage tongue carcinoma with high expression of TB showed high expression of LAMC2 in TB-expressing cells and in tumor cells bordering the stroma, even in the tumor mass." (PMID 40244200, 2025).
acute lymphoblastic leukemia (1 paper, 2018). Leukemia with an acute onset, characterized by the presence of lymphoblasts in the bone marrow and the peripheral blood. "Moreover, the lnc-LAMC2–1:1 rs2147578 polymorphism is also considered a possible risk factor for acute lymphoblastic leukemia (ALL) in children." (PMID 30285664, 2018).
and neck cancer (1 paper, 2024). "and neck cancer (HNC), the invasion-associated molecules LAMA3, LAMC2, THBS1, IGF1R, PDGFB, and transforming growth factor β1 can serve as prognostic indicators or molecular therapeutic targets to improve the survival rates of HNC." (PMID 38877482, 2024).
bladder (1 paper, 2020). "Besides, LAMC2 with a higher methylation level and lower expression level were presented in bladder patients." (PMID 32640634, 2020).
breast tumors (1 paper, 2024). "To validate the relationship among β4, ZEB1, and LAMC2 in human tumors, we compared their mRNA levels in breast tumors (n = 1980) using data available from the METABRIC consortium." (PMID 38508310, 2024). "We extended our initial observations on TAZ-mediated repression of LAMC2 to two different organoids (patient-derived organoids, PDO41 and PDO56) that we established from freshly harvested breast tumors." (PMID 38508310, 2024).
cholesteatoma (1 paper, 2012). A pathologic process characterized by the proliferation of keratinizing squamous epithelium resulting in the accumulation of keratin and cells in the middle ear and/or mastoid. "Moreover, tumor suppressor genes CDH18, 19 and ID4, which are known to be down-regulated in various tumors PAX3, LAMC2 and TRAF2B are also down-regulated in cholesteatoma." (PMID 23285167, 2012).
colitis (1 paper, 2022). Inflammation of the colon. "Lamc2 and Traf3 are usually overexpressed in the colitis, and both of them would further aggravate inflammation." (PMID 35565775, 2022).
cystadenoma (1 paper, 2022). A benign or borderline cystic epithelial neoplasm arising from the glandular epithelium. "Levels of LAMC2 were significantly higher in cystadenoma and pancreatitis patients compared to healthy donors (p < 0.0001)." (PMID 35681634, 2022).
enamel hypoplasia (1 paper, 2023). "Individuals with EB caused by mutations in laminin-332 (Lama3, Lamb3, Lamc2), α6ß4-integrin (TGB4, ITGA6) gene and type XVII collagen (Col17A1) are associated with enamel hypoplasia." (PMID 37511997, 2023).
endometriosis (1 paper, 2013). The growth of functional endometrial tissue in anatomic sites outside the uterine body. "In this study, LAMC2 mRNA was found to be differentially expressed in the ectopic endometrium of women with endometriosis compared with their eutopic endometrium." (PMID 24070183, 2013). "When RT-PCR was performed in paired samples of ectopic and eutopic endometrium of women with endometriosis, an up to 3 fold increase of LAMC2 mRNA levels was detected in the ectopic endometrium (P < 0.05)." (PMID 24070183, 2013). "The aim of this study was to investigate the expression of the laminin gamma 2 chain (LAMC2) in the tissues of women with and without endometriosis." (PMID 24070183, 2013). "Endometrial tissue from women with or without endometriosis showed constitutive expression of LAMC2 mRNA throughout the menstrual cycle." (PMID 24070183, 2013). "Similar LAMC2 mRNA levels were observed in the eutopic endometrium of women with and without endometriosis." (PMID 24070183, 2013). "However, when analysing LAMC2 mRNA levels, we did not observe differences between eutopic endometrium from women with and without endometriosis." (PMID 24070183, 2013).
Failure to thrive (1 paper, 2006). Failure to thrive (FTT) refers to a child whose physical growth is substantially below the norm. "Lamc2-/- mice die within 3–5 days of birth presumably due to failure to thrive and involvement of the oral and gastroesophageal mucosa." (PMID 16483354, 2006).
invasive ductal carcinoma (1 paper, 2020). "For validation, the feature and spatial feature plots of MAF, CD248, GJA1, LAMA3, TJP1, LAMC2, and COL17A1 demonstrated to show the location in BRCA samples, and they were highly-expressed in the invasive ductal carcinoma tissue (cluster 2, 4, 7, 9, 12)." (PMID 33585235, 2020).
kidney cancer (1 paper, 2022). Primary or metastatic malignant neoplasm involving the kidney. "Of the three members of the LAMC family, LAMC1 and LAMC2 were upregulated in kidney cancers, while LAMC3 was downregulated in kidney cancers." (PMID 36188228, 2022).
leukoplakia (1 paper, 2024). A white patch or plaque on a mucous membrane that cannot be characterized clinically or pathologically as any other disease. "LAMC2 may be a predictive marker for the malignant progression of leukoplakia." (PMID 38540190, 2024).
liver fibrosis (1 paper, 2026). "The transcription factors associated with LAMC2 in liver fibrosis were predicted and verified." (PMID 41737731, 2026). "This study provides new insights and highlights the promising potential of the SMC1A/LAMC2/PI3K/Akt axis as a therapeutic target for liver fibrosis." (PMID 41737731, 2026). "Laminin subunit gamma 2 (LAMC2) is an ECM protein whose functional role in hepatic fibrosis remains to be fully elucidated." (PMID 41737731, 2026). "Herein, we examine how LAMC2 contributes to liver fibrosis and explore the molecular mechanisms in both animal and cellular models." (PMID 41737731, 2026). "LAMC2 was knocked down in C57BL/6J mice with CCl4-induced liver fibrosis." (PMID 41737731, 2026). "LAMC2, which was enriched in the PI3K/Akt pathway, was increased in the liver tissues of mice treated with CCl4, and recilisib reversed LAMC2 knockdown-mediated alleviation of liver fibrosis in these mice." (PMID 41737731, 2026).
lymph node metastasis (1 paper, 2023). "LAMC2 expression was correlated with worse survival, lymph node metastasis, tumor-node-metastasis stages, and tumor status." (PMID 37835529, 2023).
metastatic cancer (1 paper, 2023). A carcinoma which has spread from the original site of growth to another anatomic site. "Metastatic cancer-1 cells highly expressed mesenchymal markers (e.g., VIM, FN1, and COL1A1), typical of EMT, whereas metastatic cancer-2 cells highly expressed partial EMT (p-EMT) signature genes (e.g., LAMC2, PDPN, and INHBA), indicative of a p-EMT phenotype." (PMID 37853464, 2023).